IL6 (interleukin 6)
Diseases named in the same sentence as IL6 in open-access papers (continued):
Sharing a sentence is not in itself a finding about the gene and the disease.
Arthritis (continued). "For Ross River virus (RRV) induced arthritis, it was speculated that inhibition of rheumatic disease with PPS treatment was due to a reduction in IL-6 and CCL2." (PMID 34492036, 2021). "The high humidity (80 ± 5%) could aggravate arthritis variables including increasing arthritis score and swelling, serum autoantibodies (anti-COII and anti-CCP), and proinflammatory cytokines (IL-6, IL-17A, and G-CSF)." (PMID 34852827, 2021). "VP treatment decreased gut TNF expression with no change for IL6, thus reflecting the immunomodulatory effect of VP described in arthritis." (PMID 34956224, 2021). "Although IL–6 has not been found to have a crucial role in the effector phase of experimental arthritis, blockade of IL–6 receptor is effective in improving clinical symptoms in RA patients." (PMID 34793561, 2021). "In all animals, IL-6 was not detectable in plasma before sensitization, and elevated production of IL-6 was observed after the onset of arthritis (Day 54)." (PMID 35126375, 2021). "The number of patients with arthritis was significantly higher in the IL-6-dominant subgroup, while no patient in the IL-18-dominant subgroup presented with arthritis." (PMID 34203779, 2021). "Eicosanoids derived from n-6 PUFAs influence the synthesis of pro-inflammatory cytokines, i.e., interleukin-1 (IL-1), interleukin-6 (IL-6), and tumor necrosis factor-α (TNF-α), which participate in the development of such skeletal disorders as osteopenia, osteoporosis, or arthritis." (PMID 34065038, 2021). "Moreover, strychnine, brucine and triptolide possessed an anti-arthritis activity as they inhibited the proliferation of FLSs and reduced the production of TNF-α/IL-6 and mRNAs levels of TNF-α, IL-6, COX-2, and iNOS." (PMID 34108880, 2021). "In particular, a crucial role is played by IL-6 and some studies have shown that the absence of this interleukin induced complete protection against arthritis in mice." (PMID 33435178, 2021). "In vivo, the effect of PS VII on the weight of the rat, paw swelling, ankle joint diameter, arthritis index, serum inflammatory cytokines (TNF-α, IL-6, and IL-1β), histopathological assessment and apoptosis proteins in the synovial tissues were evaluated in AIA rats." (PMID 34122110, 2021). "Proinflammatory cytokines, such as IL-6 and tumor necrosis factor (TNF)-α, have been shown to sensitize nociceptors in rats, whereas TNF-α blockade attenuated pain behaviors and joint destruction in a mouse model of arthritis." (PMID 33808727, 2021). "In addition, brucine, strychine and triptolide significantly inhibited the expression of arthritis-related inflammatory factors (i.e., TNF-α, IL-6, COX-2, and iNOS)." (PMID 34108880, 2021). "Furthermore, ursolic acid reduced the incidence and severity of CIA-induced arthritis, accompanied by the decreased expression of TNF-α, IL-1β, IL-6, IL-21, and IL-17 in arthritic joints." (PMID 32116720, 2020). "Arthritis induced by colonic SKG T cell transfer is characterized by lymph nodes’ and ankles’ enrichment with RORγt-expressing T cells, a population that in healthy mice is highly enriched in the colon and whose generation is dependent on IL-6." (PMID 33055428, 2020). "The arthritis-related genes IL1β, IL6 and TNFα were only found up-expressed in Ficat IV stage which indicated that the arthritis-related molecular changes were not significant in the progression of ONFH before Ficat III stage." (PMID 30671313, 2019). "Our results demonstrated that the severity of arthritis was improved by suppressing serum inflammatory cytokines and the synovium cytokine mRNA expressions (especially those of IL-18, IFN-γ, TNF, and IL-6) and by suppressing the accumulation of CD4+ T cells in IL-18Rα KO mice." (PMID 31861496, 2019). "Although mice in this group made a full recovery, the serum across the groups showed a high variation of IL-6, MCP-1 and TNF-α; therefore, no conclusion can be drawn as these are more likely to be the result of a cytokine storm than arthritis." (PMID 30713718, 2019).
Arthritis (continued). "In addition, we also found that RFX1 expression level was negatively correlated with serum C-reactive protein (CRP) level, a surrogate marker of IL-6 activity, in SLE patients with active arthritis." (PMID 29422534, 2018). "IL-1 and TNF-α were required for arthritis induced by the transfer of anti-type II collagen antibodies (CAIA), while IL-6 was imperative for arthritis induced by the immunization with type II collagen (CIA), because IL-6 was essential for the differentiation of Th17 cells." (PMID 28753982, 2017). "Collectively, these data suggest that the inhibitory effect of PLAG on IL-6 and MIP-2 expression in joint synoviocytes may be used to prevent arthritis development and joint destruction." (PMID 29228558, 2017). "Non-MHC genes that influence rat PIA arthritis severity include TNFα, IL-1β, IL-6, IL-17, and CCL-2, and joint damaging MMPs." (PMID 29145473, 2017). "Plasma IL-6 levels didn’t correlate with the arthritis score (r = -0.04, p = 0.83, not shown) but correlated with the ankle diameter." (PMID 28759646, 2017). "In TNF-α transgenic mice, arthritis was completely inhibited by IL-1 deficiency, suggesting that IL-1 acts downstream of TNF-α, while IL-6 was not required for the development of arthritis in this animal model." (PMID 28753982, 2017). "Finally, the role of IL-6 and TGF-β1 changes from immunosuppressive in resolving arthritis to stimulatory very early in the development of RA." (PMID 28847766, 2017). "In mice with AIA, absence of IL-6 and IL-21 signaling more strongly reduced Th17 levels and resulted in stronger suppression of arthritis than the absence of either cytokine." (PMID 28158305, 2017). "Notably, however, similar to what was observed in the hypothalamus, in Charles River rats, mean levels of IL-1β, IL-6, and MCP-1 were highest in rats that developed severe arthritis (Adj/S) whereas in Harlan rats, mean cytokine levels were highest in controls." (PMID 28386080, 2017). "The results show that WJHL can significantly alleviate the progression of CIA, reduce ankle swelling, arthritis score, pathological changes, and bone destruction, and increase the level of OPG by inhibiting the levels of TNF-α, IL-1β, IL-6, and IL-17 in the serum of CIA mice." (PMID 28562338, 2017). "In mice, overexpression of IL-6 leads to arthritis while absence of IL-6 prevents formation of arthritis in an experimental murine system." (PMID 28289415, 2017). "In addition, compared with arthritis control, PDCD5 tg mice reduced serum levels of the pro-inflammatory cytokines IFN-γ, IL-6, IL-17A and TNF-α and upregulated the expression of the anti-inflammatory cytokine IL-4." (PMID 29228993, 2017). "To explore further the role of GM-CSF as a pro-inflammatory cytokine, we examined the effect of anti-GM-CSFRα neutralization on myeloid cell populations in antigen-driven arthritis and inflammation models and also compared its effect with that of anti-TNF and anti-IL-6." (PMID 27908288, 2016). "In addition, ChondroT decreased the expression of inflammatory enzymes COX-2 and iNOS and reduced the production of inflammatory mediators, such as IL-1β, IL-6, PGE2, and NO, thereby playing important roles in arthritis." (PMID 27411719, 2016). "Thus, proinflammatory cytokines (particularly IL-1β, IL-6, and TNF-α) play an important role in arthritis onset, while inhibitors of these cytokines are effective in controlling chronic inflammation." (PMID 27382402, 2016). "With regards to pro-inflammatory cytokines, IL-1β correlates with and partially precedes the course of clinical arthritis, whereas serum IL-6 and TNFα are not changed during PIA." (PMID 27227821, 2016). "The infiltrated immune cells and synovial fibroblasts secrete various cytokines, like TNF-α, IL-1β, and IL-6, metalloproteinases (MMPs), and chemokines, such as MCP-1, MIP-1, and RANTES, in the inflamed joint tissues and eventually lead to arthritis including inflammation and bone erosion." (PMID 27840652, 2016).
Arthritis (continued). "Likewise, the intra-articular injection of mBSA that triggers arthritis in AIA, is accompanied by a strong recall response of proinflammatory cytokines in serum, including IL-6, IL-10, IL-12, and TNF." (PMID 26512984, 2015). "IL-6, as well as TNF, IL-1β and PGE2, were reported to up-regulate the RANKL (receptor activator of NF-κB ligand) expression, which was an important prerequisite for osteoclast differentiation and arthritis." (PMID 25602164, 2015). "Therapeutic blockade of TNF could yield rapid decrease of plasma IL-6 level, and our previous study based on rat model of arthritis has revealed that HMLE strongly inhibited the excessive production of both TNF and IL-6." (PMID 25602164, 2015). "OPN-deficient mice exhibit reduced disease in arthritis models not by altering TNF-α levels but by suppressing angiogenesis in the joints, and angiogenesis is enhanced by IL-6 signaling instead of by TNF-α." (PMID 26698858, 2015). "Myeloid cells exhibit excessive proliferation and infiltration into joint tissue of B6 miR-146a−/− mice, have increased phagocytic activity and produce excess cytokines such as IL-1β, IL-6 and CXCL1, leading to inflammation of synovial tissue and arthritis development." (PMID 24967703, 2014). "Likewise, recombinant Hsp72 (induced Hsp70) has been reported to lessen the severity of collagen-induced arthritis in mice, by lowering serum TNF-α and IL-6 concentration." (PMID 25053922, 2014). "In our study of K/BxN serum-induced arthritis, IL-12 p40 levels had not been different, and IL-6 and M-CSF levels tended to be altered in tg mice in comparison to WT mice (IL-1α and IL-13 levels were not determined)." (PMID 24491163, 2014). "Osteopontin and IL-6 are rather unlikely to be responsible because they play no essential role in K/BxN arthritis." (PMID 24491163, 2014). "The anti-arthritis effects of melittin, an HBV constituent, are suggested to be decrease in COX-2 and phospholipase A2 expression and decline in the levels of TNF-alpha, IL-1, IL-6 and ROS." (PMID 24330637, 2013). "Interestingly, studies demonstrated that NFKBIZ mediated IL-6 production, ADRB2 antagonists reduced the severity of arthritis, and that anti-CXCL16 antibody inhibited infiltration of inflammatory cells and arthritis." (PMID 23936839, 2013). "Thus, the induction of IL-6 via PGRN is a possible explanation for the fact that PGRN levels are correlated with anemia and arthritis." (PMID 23140401, 2012). "TNF-α and IL-6 mRNA expressions in whole hind limbs were up-regulated in immunized mice with arthritis compared with intact mice, and MTX treatment did not reduce TNF-α or IL-6 mRNA expressions." (PMID 22546471, 2012). "In the CIA model, we confirmed the role of IL-6 and PGE2 in the suppressive activity of MSCs since IL-6−/− MSCs exhibited the lowest suppressive effect and did not significantly reduce the severity of arthritis as compared to wt MSCs." (PMID 21151872, 2010). "Anti-IL-6 therapy exhibits a trend towards the suppression of disease progression, as the majority of treated animals did not progress to arthritis in two paws." (PMID 19368720, 2009). "A cohort study involving patients with ICI-induced arthritis and matched controls revealed significantly elevated serum levels of vascular endothelial growth factor-A (VEGF-A) and TNF-α in the ICI-induced arthritis group, along with increased levels of IFN-γ and IL-6." (PMID 41239350, 2025). "In the present experiments, we tested the hypothesis that IL-6 signaling activates EGFR signaling in peripheral and spinal nociception and examined whether EGFR localization and activation coincide with pain-related behaviors in arthritis." (PMID 39000275, 2024). "The zymosan-induced arthritis model is characterized by the release of pro-inflammatory cytokines, such as tumor necrosis factor (TNF), interleukin-18 (IL-18), interleukin-1β (IL-1β), and interleukin-6 (IL-6); synovial joint hypertrophy; and leukocyte recruitment." (PMID 39194751, 2024).
Arthritis (continued). "IL-6 blockade may be preferred to IL-1 blockade in arthritis-dominant patients, but comparative studies are lacking." (PMID 37669122, 2024). "However, it is noteworthy that systemic inflammation in combination with arthritis is observed in IL-1-overexpressing, but not IL-6-overexpressing transgenic mice." (PMID 36911042, 2023). "Lymph node cells were isolated from model rats and administered with DAPs, and it was found that the expression levels of IL-1β, IL-2, IL-6, TNF-α and IFN-γ were significantly reduced, while the acceleration of arthritis severity could be attributed to the elevation of these factors." (PMID 36235835, 2022). "We found that MCP-1/CCL2 and IL-6 were significantly lower in SSR240612-treated WT mouse arthritic ankle homogenates in comparison with vehicle-treated WT mice, suggesting that B1R plays an important role in the expression of these cytokines in K/BxN serum–induced arthritis." (PMID 35439173, 2022). "Iguratimod is a new antirheumatic drug that suppresses the production of tumor necrosis factor α (TNFα), interleukin 6 (IL-6), and IL-8 in lipopolysaccharide-stimulated THP-1 cells, and inhibits cartilage and bone damage in DBA/1J mice with type II collagen (COL-II)-induced arthritis." (PMID 35387545, 2022). "In effect, bone erosions in arthritis result from the combination of multiple signals that include high levels of RANKL in FLS, B, and T cells; the inflammatory cytokines TNFα, IL-1, and IL-6, both in RANKL dependent and independent pathways; and anti-CCP and other RA autoantibodies." (PMID 36032152, 2022). "Blocking IL-6 signaling reduced arthritis scores but did not block the incidence of arthritis." (PMID 34901991, 2022). "In the CIA model mice, this study successfully demonstrated that the high humidity could aggravate RA variables including increasing arthritis scores and swelling, serum autoantibodies (anti-COII and anti-CCP), and proinflammatory cytokines (IL-6, IL-17A, and G-CSF)." (PMID 34852827, 2021). "Moreover, strychnine, brucine, and triptolide significantly inhibited the proliferation of fibroblast-like synoviocytes, and reduced the production of TNF-α and IL-6 and the mRNAs of TNF-α, IL-6, COX-2, and iNOS, suggesting that they possessed an anti-arthritis activity." (PMID 34108880, 2021). "The postulation that deficiency of A20 leads to a plethora of inflammatory IL-6 that drives Th17 differentiation has been confirmed in an arthritis-related study where A20 inhibits Th17 cell differentiation through IL-6 in mice lacking A20 in their bone marrow mesenchymal stem cells (BM-MSCs)." (PMID 34557201, 2021). "Zymosan caused systemic inflammation with a marked elevation in multiple pro- and anti-inflammatory cytokines TNF-α, IFN-γ, IL-13, G-CSF, M-CSF, IL-6, IL-18, IL-1α and IL-4 in arthritic rats (all arthritis groups pooled) versus the non-arthritic controls (0.001<p<0.05)." (PMID 33878143, 2021). "However, in the 8-week-old mice,this same procedure failed to develop arthritis and also to increase serum IL-6 levels." (PMID 33833871, 2021). "The patterns of inflammatory cytokine concentrations in serum are reported to differ from arthritis and paw swelling scores in CIA mice, which may be attributed to the potential involvement of other factors in improving pro-inflammatory IFNγ or IL6 levels in blood." (PMID 32549254, 2020). "Ingenuity pathway analysis identified inflammatory pathways in arthritis along with classic cachexia pathways, including PI3K/Akt signaling, acute phase response signaling, STAT3 pathway, NF-kB signaling, coagulation and complement system, and IL-6 signaling pathways." (PMID 33334063, 2020). "Our study suggested that the targeting IL-6 and COX-2 may attenuate PMs-induced arthritis." (PMID 32498294, 2020).
Arthritis (continued). "However, when considering the subgroup of microcrystal-induced arthritides, IL-6 significantly decreased in ice-treated patients (N = 19) but also in the 3 microcrystal-induced arthritis patients of phase II (data not shown)." (PMID 31362785, 2019). "Indeed, in collagen-induced arthritis (CIA), BM-MSCs did not hamper the development of arthritis and rather accelerated it through enhancement of IL-6 production." (PMID 31722720, 2019). "Moreover, we found that seronegative UPIA patients who differentiate into further defined arthritis, show higher expression of lining and sublining CD68+ cells, sublining CD3+ cells, increased number of CD31+ vessels and higher IL-6 PB levels than patients who remain as UPIA during the follow-up." (PMID 30018954, 2018). "The role of osteoclast formation in arthritis and bone erosion has been well described and it was already reported that HSF played an important role on bone erosion through their ability to secrete a large panel of cytokines such as IL1β, IL-6, M-CSF, GM-CSF and RANKL." (PMID 30074983, 2018). "Furthermore, a single injection of tocilizumab causes an increase in circulating IL-6 levels but does not affect IL-6 gene expression in the liver or other organs from monkeys with experimental arthritis." (PMID 29078808, 2017). "In addition, study demonstrated that the absence of IL-6 induces complete protection against arthritis in CIA mice and an anti-mouse IL-6R monoclonal antibody inhibits development of arthritis in CIA mice." (PMID 27122657, 2016). "In addition, it did not affect IL-17 cytokine in the joint of animals with arthritis, although it exerted an inhibitory effect on the release of IL-6." (PMID 27819273, 2016). "Reduced production of T cell-polarizing cytokines such as IL-6 and IL-23 by myeloid pten-/- APCs in vitro as well as in vivo after induction of CIA leads to reduced generation of IL-17- and IL-22-producing T cells, which in turn are required to induce arthritis in CIA animals." (PMID 26307404, 2015). "Thus, the treatment of JWH133 could suppress other inflammatory mediators than IL-6, CCL2 and MMP-3, which are involved in pathology of the arthritis." (PMID 25115332, 2014). "Although IL-1 and TNFα, but not IL-6, were shown to be important in this arthritis model 13, it has not been clear whether IL-17 works in the effector phase of arthritis, regardless of the findings that non-T cells produce IL-17." (PMID 23671588, 2013). "However, another arthritis model, anti-type II collagen antibody-induced arthritis, bypasses the priming phase of T-cell-dependent antibody generation and is not suppressed in IL-6−/− mice." (PMID 23133751, 2012). "Despite a recent report that IL-6 but not the signal transducer gp130 is up-regulated in neuropathic rats gp130 seems to play a crucial role in pathological pain since antagonizing sgp130 prevents acute nociceptor sensitization in experimental arthritis." (PMID 21951917, 2011). "While the available data suggest that IL-6 (trans)signalling may be important for pain and inflammation, no study has investigated how neutralization of IL-6 transsignalling affects pain in an arthritis model." (PMID 20626857, 2010). "Here we tested in a preclinical model of arthritis, antigen-induced arthritis (AIA) in the rat, whether systemic or local neutralization of IL-6/sIL-6R complexes with soluble glycoprotein 130 (sgp130) alters arthritic pain and how sgp130 influences the inflammatory process in AIA." (PMID 20626857, 2010). "However, administration of IL-6 antagonist did not produce any remedial effects when administered after the onset of arthritis in CIA animals." (PMID 18534002, 2008). "Following treatment, serum levels of IL-6 and IL-17A were considerably lower at all triptolide time points, and intergroup comparisons revealed that the time of administration did not affect triptolide’s effect on arthritis score and IL-6 reduction in CIA mice." (PMID 40918529, 2025).